NES (nestin)
Diseases named in the same sentence as NES in open-access papers (continued):
Sharing a sentence is not in itself a finding about the gene and the disease.
hepatocellular carcinoma (16 papers, 2008 to 2026). A malignant tumor that arises from hepatocytes. "This association between nestin and chemotherapy sensitivity has also been reported for hepatocellular carcinoma." (PMID 32903755, 2020). "Nestin expression has been reported to be associated with the prognosis of many solid tumors including human hepatocellular carcinoma (HCC)." (PMID 27412382, 2016). "Nestin-expressing progenitor-like cells that are dedifferentiated from mature hepatocytes evolve into cholangiocarcinomas or hepatocellular carcinomas." (PMID 34772403, 2021). "Nestin expression in tumor cells reportedly led to chemoresistance in a hepatocellular carcinoma cell line and radioresistance in a nasopharyngeal carcinoma cell line." (PMID 32903755, 2020). "Accordingly, clusters of nestin-positive parenchymal cells have been observed in hepatocellular carcinoma slices." (PMID 26018884, 2015). "Regardless of the role that nestin expression plays in endothelial cells, the conspicuous pattern shown here makes hepatocellular carcinoma samples a useful alternative positive control for nestin for the following reasons." (PMID 26018884, 2015). "The presence of nestin-positive endothelial cells in hepatocellular carcinoma suggests that there is a remarkable degree of angiogenesis." (PMID 26018884, 2015). "Hepatocellular carcinoma sections from one case were analyzed for nestin expression by immunohistochemistry using confocal microscopy." (PMID 26018884, 2015). "In the light of recent reports describing nestin-positive parenchymal cells in hepatocellular carcinoma, we aimed to use this tumor type as a positive control for immunohistochemical detection of nestin." (PMID 26018884, 2015). "The gene mutation related to Nestin expression might have a significant role in the carcinogenesis of ICC and hepatocellular carcinoma mixed tumors and can serve as a biomarker for the diagnosis and prognosis of combined hepatocellular–ICC." (PMID 38203635, 2023). "Additional studies are needed to determine whether other types of nestin-expressing cells could give rise to hepatocellular carcinoma endothelial cells." (PMID 26018884, 2015). "Additionally, nestin is a broadly used molecule in regenerative medicine and in oncology research, yet a PubMed search (as of April 2, 2014) with the keywords “hepatocellular carcinoma” and “nestin” resulted in only three articles." (PMID 26018884, 2015). "Finally, hepatocellular carcinoma is an effective positive control for nestin staining in fluorescent immunohistochemistry." (PMID 26018884, 2015). "Our finding of significant nestin expression in hepatocellular carcinoma endothelial cells may clarify some aspects of the role of nestin in the proliferation and angiogenesis of this tumor type." (PMID 26018884, 2015). "Moreover, nestin expression in endothelial cells of hepatocellular carcinoma enhances the role of angiogenesis in this tumor type, although the prevalence of this immunohistopathological pattern remains to be determined." (PMID 26018884, 2015). "Our group studied Nestin expression and localization in the liver, finding a basal immunohistochemical expression in the portal arterioles: sinusoids usually do not show Nestin positivity, with the noteworthy exception of neoplastic sinusoids during hepatocellular carcinoma progression." (PMID 36138808, 2022). "Finally, hepatocellular carcinoma samples may serve as a useful positive control for nestin in immunohistochemistry experiments." (PMID 26018884, 2015). "Finally, the nestin pattern shown here, i.e. hepatocellular carcinoma with elevated nestin expression in endothelial cells, may motivate additional studies to determine its prevalence and prognostic implication." (PMID 26018884, 2015).
hepatocellular carcinoma (continued). "Moreover, it has been suggested that hepatocellular carcinoma is a positive control for nestin expression, because of the staining of parenchymal cells, according to the data sheet from a commercially available anti-nestin primary antibody." (PMID 26018884, 2015). "Nestin and CD133 are also expressed in other cancer stem cells, like hepatocellular carcinoma stem cells." (PMID 36321378, 2023). "In patients with hepatocellular carcinoma (HCC) recurrence, the majority of hepatic stem/progenitor cell (HSC/HPC) biomarkers are overexpressed, including cytokeratin 19, ABCG2, CD133, Nestin, and CD44, and angiogenesis agents CD34, VEGF, and PD-ECGF." (PMID 32466488, 2020).
prostate carcinoma (16 papers, 2010 to 2023). A carcinoma that arises from epithelial cells of the prostate gland. "Specifically, over-expression of PDGF-D caused EMT phenotype in PC3 prostate cancer cells with loss or relocation of E-cadherin and increased expression of Vimentin and Nestin, suggesting that PDGF-D overexpression contributes to EMT in human cancers." (PMID 24158561, 2013). "Finally, the ability of other cancers, such as pancreatic ductal adenocarcinoma and prostate cancer, to metastasize to the lung has been positively associated with nestin expression." (PMID 34943921, 2021). "Also of note, the developmental transcription factor SOX4, upregulated in DU145, has been shown to possess oncogenic activity in prostate cancer, wheres Nestin has been associated with the drug resistant prostate stem population." (PMID 28038472, 2017). "The CTP stemness phenotype was confirmed by the spheroids detected in CTP-DB and -BL cultures in addition to the high expression of nestin, Nanog, and SOX2, which are shown to be linked to prostate cancer development, progression, invasion, and metastasis." (PMID 37894361, 2023). "In this study, angiogenesis was assessed in prostate cancer by dual Nestin-Ki67 IHC along with the quantitative mpMRI-parameters Ktrans and kep from anatomically matched tumour areas." (PMID 37863961, 2023). "Here, we studied microvascular proliferation by Nestin-Ki67 co-expression in prostate cancer, focusing on relations to quantitative imaging parameters from anatomically matched areas obtained by preoperative mpMRI, clinico-pathological features and prognosis." (PMID 37863961, 2023). "For instance, prostate cancer cells lose their ability to migrate after treatment with siRNA against Nestin." (PMID 27894083, 2016). "The expression of NANOG, OCT4, CD133 and NESTIN in prostate ADCs with high Gleason scores (>3+4) was greater than that in prostate cancers with low Gleason scores (<3+3), although this difference was not significant." (PMID 25120646, 2014). "In prostate cancer, nestin is expressed in 75% of lethal androgen-independent prostate cancer cases." (PMID 22580387, 2012). "For example, AR- P63-CD44+Nestin+ HPET-5 cells were purified from prostate cancer cell lines and shown to recapitulate prostate-like structures in the mouse kidney after transplantation." (PMID 21241512, 2011). "Interestingly, nestin KD of PC-3 prostate cancer cells by siRNA increases focal adhesion size and invasion by affecting the distribution of phosphorylated FAK and integrin α5." (PMID 36231009, 2022). "In addition, the upregulation of NESTIN has been found to closely correlate with the malignancy and metastasis of a variety of malignancies, including prostate cancer." (PMID 25120646, 2014). "Additionally, Nestin seems to play a role in pathogenesis and it is expressed in several types of malignancies, such as osteosarcoma, neuroblastoma, glioma, melanoma, pancreatic and prostate cancers as well as in tumor vasculature." (PMID 29541793, 2018). "When specimens were diagnosed as prostate cancer, immunohistochemical analysis of the four different stem cell markers (NANOG, OCT4, CD133 and NESTIN) and hypoxia-inducible factor (HIF)-1α was performed." (PMID 25120646, 2014). "The immunohistochemical intensity of prostate cancer was weakest for NANOG followed by OCT4, with the strongest staining for CD133 and NESTIN." (PMID 25120646, 2014). "The results of this study showed that of the four CSC markers examined (NANOG, OCT4, CD133 and NESTIN), NANOG was intensively expressed in prostate cancer." (PMID 25120646, 2014). "In contrast, nestin has no role in regulating the migration of prostate cancer PC-3 cell line." (PMID 36231009, 2022). "All prostate cancers were histopathologically identified as adenocarcinomas of various grades, and cancer cells and intraepithelial neoplasia (high grade) were immunohistochemically shown to express NANOG and OCT4, but not CD133 and NESTIN." (PMID 25120646, 2014).
Hydrocephalus (15 papers, 2009 to 2023). Hydrocephalus is an active distension of the ventricular system of the brain resulting from inadequate passage of CSF from its point of production within the cerebral ventricles to its point of absorption into the systemic circulation. "Mpdz inactivation using the Nestin‐Cre line further indicated that defects in the ependyma are the primary cause of hydrocephalus." (PMID 28500065, 2017). "Knockdown of nestin in zebrafish embryo by morpholino injection causes distinct morphological changes characterized by small head, small eyes and overt hydrocephalus." (PMID 20174467, 2010). "In all of these experiments the Nestin-Cre transgene was employed as a heterozygous allele, since homozygosity of a similar transgene was previously reported to cause hydrocephalus itself." (PMID 19774080, 2009). "We used the Nestin-Cre mouse line previously employed to inactivate Stumpy, another ciliary protein reported to cause hydrocephalus when inactivated." (PMID 19774080, 2009). "In light of the effects of Ecrg4 expression on cell proliferation (BrdU) and differentiation (nestin), it is more likely that this hydrocephalus phenotype is caused by increased ventricular cell proliferation resulting in obstruction of CSF flow and drainage during development." (PMID 21349154, 2011). "Global Mpdz gene deletion or conditional inactivation in Nestin‐positive cells led to formation of supratentorial hydrocephalus in the early postnatal period." (PMID 28500065, 2017). "As treatment with 10 ng nestin MO1 induced hydrocephalus and eye changes in a majority of embryos, we performed subsequent experiments by microinjection of 10 ng MO1." (PMID 20174467, 2010). "Nestin morphants exhibited characteristic morphological changes including small head, small eyes and hydrocephalus." (PMID 20174467, 2010). "A magnified view of nestin MO-treated embryos at 51 hpf showed characteristic morphological abnormalities including small head, reduced brain size and hydrocephalus as well as small and poorly organized eyes." (PMID 20174467, 2010). "Using hydrocephalus as an index of brain abnormalities, we found the effect of nestin MO on brain development was dose-dependent." (PMID 20174467, 2010). "In fact, we have observed a mild hydrocephalus both in Pkd1 mutant embryos and in newborn conditional mice carrying a Nestin-Cre transgene." (PMID 19774080, 2009). "Importantly, three different Nestin-Cre mouse strains were shown to develop hydrocephaly due to high amounts of Cre recombinase expression in neural progenitor cells." (PMID 36846208, 2023). "Neural cell-specific knockout of Hif1α using Nestin-Cre driver causes massive apoptosis in the cerebrum at E19, resulting in hydrocephalus at P70, while no gross morphological differences can be observed in E15 embryos." (PMID 35361248, 2022). "This suggests that the thinning of the lateral cortices and the enlargement of the lateral ventricles in Arpc2f/f Nestin-Cre mouse embryos might be due to pressure generated from severe hydrocephalus." (PMID 27385014, 2016). "Earlier activation of E545K mutation with Nestin-cre led to an even more striking 54.4% volumetric increase, with mild ventriculomegaly and no hydrocephalus." (PMID 26633882, 2015). "Indeed, Nestin‐Cre+/+;MpdzΔ/Δ mice developed hydrocephalus in the early postnatal period." (PMID 28500065, 2017). "The Pkd1Flox/−;Nestin-Cre mice develop massive renal cystogenesis after birth, eventually causing death of the mice due to renal failure by day P12 (not shown), thus preventing us from studying the effect on hydrocephalus at later time points." (PMID 19774080, 2009). "In this study, we aimed to clarify the role of afadin in the brain by using the nestin-Cre-mediated cKO mice of the afadin gene and described that the afadin-cKO mice developed noncommunicative hydrocephalus, owing to the developmental defect in the midbrain." (PMID 24236178, 2013).
Hydrocephalus (continued). "Although homologues of Lgl1 and aPKC in Drosophila regulate Hippo (hpo) kinase activity by modulating dRassf inhibition of hpo39, we found that double conditional knockout of Mst1/2, the mammalian homolog of hpo, with Nestin Cre did not elicit a hydrocephalus phenotype (unpublished data)." (PMID 26754915, 2016). "In addition, Pkd1Flox/+;Nestin-Cre brains were used as negative controls and none developed any sign of hydrocephalus, excluding the possibility that the transgene alone induced this phenotype in the heterozygous state." (PMID 19774080, 2009). "To determine whether hydrocephalus in the Yap CKO (used throughout this manuscript to refer to Yapflox/flox; Nestin Cre) was non-communicating or communicating, we assessed whether dye injected into one lateral ventricle could diffuse freely into the fourth ventricle." (PMID 26754915, 2016).
non-small cell lung carcinoma (13 papers, 2013 to 2025). A group of at least three distinct histological types of lung cancer, including non-small cell squamous cell carcinoma, adenocarcinoma, and large cell carcinoma. "Nestin expression is associated with different aspects of carcinogenesis and tumor progression in several types of cancer and, especially, in non-small-cell lung cancer." (PMID 39941813, 2025). "Aberrant expression of nestin is linked to poor prognosis in different cancers, including non-small cell lung cancer." (PMID 32903755, 2020). "Loss of Nestin sensitizes non-small cell lung carcinoma (NSCLC) to oxidative stress." (PMID 31695040, 2019). "Nestin competes with Nrf2 for binding to Keap1, thereby promoting the production of antioxidant enzymes, enhancing the antioxidant stress resistance in non-small cell lung cancer and gastric cancer, and consequently contributing to drug resistance." (PMID 40799240, 2025). "Knockdown of nestin expression significantly inhibit the proliferation and colony formation of non-small cell lung cancer, leading to G1 phase of the cell cycle and inhibiting AKT activation." (PMID 40799240, 2025). "In non-small cell lung cancer, Nestin interacts with the Kelch domain of Keap1, leading to the escape of Nrf2 from Keap1-mediated degradation and subsequent promotion of antioxidant enzymes." (PMID 39354366, 2024). "This suggests that the Nestin–Keap1–Nrf2 axis functions as a regulator of cellular redox homeostasis and confers resistance to oxidative stress in non-small cell lung cancer." (PMID 39354366, 2024). "For example, the involvement of the nuclear envelope protein nestin, which stabilizes lamin-A/C through interaction with the rod domain of nestin, is reported against proteasomal degradation of lamin-A/C in non-small-cell lung carcinoma A549 cells." (PMID 37250905, 2023). "Subsequent studies have revealed that nestin knockdown inhibits cell proliferation and G1/S arrest in human non-small cell lung cancer cells, possibly via downregulation of AKT-GSK3β-cyclin D signaling." (PMID 24966803, 2014). "Nestin is a marker of neural progenitor cells and is frequently expressed in cancer cells of non-small cell lung carcinomas." (PMID 24160469, 2013). "In the present study, using non-small-cell lung carcinoma (NSCLC) model cell lines, we investigate the nuclear localization and functional roles of Nestin and reveal Nestin can import into the nucleus through a classical nuclear localization signal (NLS)." (PMID 30190500, 2018).
astrocytoma (12 papers, 2006 to 2025). "Significant changes in these proteins (particularly GFAP and nestin), which are associated with motility and invasiveness, have been described in the astrocytoma cell lines." (PMID 16457706, 2006). "The findings that nestin knockdown reduces cultured neuroblastoma and astrocytoma cell growth while its overexpression has a cytoprotective effect against H2O2 injury suggest a role in the promotion of cell survival and proliferation." (PMID 24498263, 2014). "The specific interfering role of Nestin siRNAs was in vitro identified on cell growth of C6 astrocytoma cells, suggesting that siRNA-induced suppression of central neural system tumor cell growth." (PMID 23016664, 2012). "The expression of Nestin in different astrocytoma cell lines has been related to a migratory cell phenotype with increased motility and invasiveness of different astrocytoma cell lines." (PMID 19108713, 2008). "Although earlier studies have reported that knockdown of nestin by siRNA effectively reduces the proliferation and growth of C6 astrocytoma cells and its downregulation activates CdK5/p35-dependent apoptotic pathways, the precise role of nestin in tumor metastasis is obscure at present." (PMID 24498263, 2014). "iPSC lines were first differentiated to forebrain-patterned SOX2+/NESTIN+/SOX10− neural progenitor cells (NPCs) and then to GFAP+ astrocytes, the cell-of-origin of astrocytoma, using a modified astrocyte differentiation protocol." (PMID 36973285, 2023). "Anaplastic astrocytoma cells expressed high levels of GFAP, while nestin expression was detected only in scattered cells." (PMID 25710480, 2015).
microcephaly (12 papers, 2010 to 2024). A congenital or acquired developmental disorder in which the circumference of the head is smaller than normal for the person's age and sex. "CHD4 likewise influences cortical development, and neuronal deletion of Chd4 with a Nestin-Cre results in lethality associated with microcephaly at birth." (PMID 32658897, 2020). "Mice with GCN5-deficient NSC exhibit a 25% reduction in brain mass with a microcephaly phenotype similar to that observed in nestin-cre driven knockouts of c- or N-myc." (PMID 22745758, 2012). "Knockout (KO) of either c-myc or N-myc genes in neural stem and precursor cells (NSC) driven by nestin-cre impairs mouse brain growth and mutation of N-myc also causes microcephaly in humans in Feingold Syndrome." (PMID 20651942, 2010). "Mice with Mysm1 knockdown by crossing Mysm1 floxed mice with Nestin-Cre mice exhibited abnormal brain development with microcephaly." (PMID 38342917, 2024). "We found that GCN5 is required in NSC for normal brain growth, producing a microcephaly phenotype similar to the nestin-cre driven myc KOs." (PMID 22745758, 2012). "Furthermore, neural tissue-specific disruption of Nbs1 and Mre11 via Nestin-cre conditional gene targeting, results in microcephaly as a consequence of massive neuroepithelial cell apoptosis." (PMID 26792133, 2016). "In studies on Zika virus-induced microcephaly, UPR activation was also found to promote direct neurogenesis, and Kira6 treatment could effectively reverse the increase of Nestin and PAX6 positive NPCs." (PMID 39521780, 2024). "Nonetheless, the surviving mice outwardly appear phenotypically normal with only a minor decrease in head size (not shown) that was suggestive of the microcephaly we have previously observed with nestin-cre mediated KO of c- or N-myc." (PMID 22745758, 2012). "Some transgenic lines also had a significant level of leakage in miRNA expression before crossing with nestin-Cre, but none showed microcephaly during line propagation in crossings with the wild type mice." (PMID 21572998, 2011).